INS (insulin)
Diseases named in the same sentence as INS in open-access papers (continued):
Sharing a sentence is not in itself a finding about the gene and the disease.
polycystic ovary syndrome (continued). "A potential reason for the increased testosterone levels in the GDM group could be polycystic ovary syndrome (PCOS), which is associated with increased insulin insensitivity and higher androgen levels, though no cases with PCOS were included in our cohort." (PMID 34209500, 2021). "In obese women with polycystic ovary syndrome (PCOS), 1000 mg/day curcumin supplementation (500 mg twice daily: 70–80% curcumin, 15–20% demethoxycurcumin and 2.5–6.5% bisdemethoxycurcumin) for six weeks improved serum insulin and the Quantitative Insulin Sensitivity Check Index." (PMID 33080891, 2020). "PCOS, polycystic ovary syndrome; HDL, high-density-lipoprotein-cholesterol; LDL, low-density-lipoprotein-cholesterol; TG, triglycerides; FPG, fasting plasma glucose; FI, fasting plasma insulin." (PMID 32187268, 2020). "Serum levels of retinol-binding protein 4 (RBP4), an adipokine thought to affect systemic insulin sensitivity, were compared between women with polycystic ovary syndrome (PCOS) and non-PCOS controls to evaluate the association of RBP4 with clinical, hormonal and metabolic parameters of PCOS." (PMID 31051472, 2019). "We found that the serum testosterone (T) and fasting insulin (fins) levels increased after the DHEA injection when compared with control rats, demonstrating that the established model reflected the primary symptoms of polycystic ovary syndrome." (PMID 29020999, 2017). "A single iv dose of ghrelin significantly increases plasma glucose levels followed by a reduction in fasting insulin levels in lean and obese subjects with or without polycystic ovarian syndrome, suggesting inhibition of insulin secretion." (PMID 26042199, 2015). "Chromium picolinate effectively reduced insulin resistant and treated hyperinsulinemia as well as hyperandrogenemia but did not significantly affect the hormonal changes." (PMID 24639797, 2013). "Clinical trials have confirmed that overweight women with polycystic ovary syndrome (PCOS) who followed a high-protein, very-low-calorie diet for 4 weeks experienced significant reductions in fasting blood glucose levels and insulin levels, as well as a significant increase in insulin sensitivity." (PMID 41377049, 2025). "By the same token, findings in an animal model of polycystic ovary syndrome (PCOS) indicated that thylakoid-treated rats showed reduced weight, attenuated HOMA-IR and insulin levels, and improved serum concentrations of lipids." (PMID 37576981, 2023). "For example, in women with polycystic ovarian syndrome (PCOS), a low carbohydrate diet could represent an alternative to pharmacological treatment with metformin, as it can reduce the stimulus on the release of insulin of the pancreatic cell by glucose." (PMID 36235799, 2022). "Moreover, none of the participants had a history of polycystic ovary syndrome (PCOS) or an abnormal level of glucose or insulin." (PMID 35740976, 2022). "One study found that eight weeks of supplementation of 200 μg of chromium in non-pregnant women with polycystic ovary syndrome (an insulin-resistant condition) led to several benefits and possibly an increase in pregnancy rate (17% vs. 3%, p = 0.08) during that eight weeks." (PMID 34071548, 2021). "Therefore, the aims were to identify the molecular mechanisms underlying electroacupuncture-induced glucose uptake in skeletal muscle in insulin-resistant overweight/obese women with and without polycystic ovary syndrome (PCOS)." (PMID 32232327, 2020). "Also, in the present study, treatment of polycystic ovary animals by sage tea did not alter insulin levels." (PMID 32523881, 2020). "Four months of daily pioglitazone treatment (30 mg) increased insulin-stimulated Rd (at similar steady-state insulin concentrations to this study) by 14% in IGT patients, while six months of daily pioglitazone treatment (45 mg) increased it by 28% in IGT patients with polycystic ovary syndrome." (PMID 25954816, 2015).
polycystic ovary syndrome (continued). "Although insulin and IGF are potent proliferative factors for the ovarian surface epithelium and IGF is required for follicle development, increased insulin and IGF activity are correlated with at least two gynecologic conditions: polycystic ovary syndrome and epithelial ovarian cancer." (PMID 23388061, 2013). "In women with polycystic ovary syndrome (PCOS), MICT and HIIE both enhance cardiorespiratory fitness (CRF) and metabolic parameters, although HIIE may yield superior insulin sensitivity and hormonal outcomes." (PMID 41421989, 2025). "BAT transplantation improves whole-body energy metabolism and ameliorates polycystic ovary syndrome (PCOS), and the transplantation of BAT into PCOS rats significantly stabilizes menstrual irregularity and improves systemic insulin sensitivity up to a normal level." (PMID 36714578, 2022). "Furthermore, high insulin levels in PCOS patients may also accelerate the pulse of LH secretion and stimulate the synthesis of androgens by follicular membrane cells, resulting in hyperandrogenemia and anovulation." (PMID 36353235, 2022). "A positive correlation was observed between PNX-14 expression and LH, FSH, and testosterone and a negative correlation with serum estradiol and insulin levels in women with polycystic ovary syndrome (PCOS)." (PMID 34680544, 2021). "Increased leptin concentration observed in women diagnosed de novo with polycystic ovary syndrome, as well as positive correlations between leptin and HOMA-IR, IRI/glucose, and BMI, may indicate a potential role of leptin in the reduction of tissue sensitivity to insulin." (PMID 34604014, 2021). "Yet, insulin stimulates IPG-P release in normal subjects but not in insulin-resistant women with polycystic ovary syndrome (PCOS)." (PMID 30595691, 2018). "Also, in rats with dihydrotestosterone- (DHT-)induced Polycystic ovary syndrome (PCOS), low-frequency EA has been shown to have systemic and local effects involving intracellular signaling pathways in muscle that may, at least in part, account for the marked improvement in insulin sensitivity." (PMID 21754922, 2011). "However, there was an investigation that could not find any connection between polycystic ovaries and insulin levels." (PMID 26396568, 2011). "In non-diabetic patients, including obesity, depression, polycystic ovary syndrome (PCOS), probiotics did not play an effective role in regulating sugar metabolism such as reducing fasting plasma glucose and quantitative insulin sensitivity check index or influencing pancreatic β-cell function." (PMID 38510031, 2024). "In another study in women with polycystic ovary syndrome, consumption of NAC at a daily dosage of 1800 mg for 6 months substantially reduced BMI, FBS, fasting insulin, HOMA index, and LDL levels but did not affect triglyceride and total cholesterol." (PMID 36448959, 2023). "Therefore, we hypothesize that LNK negatively regulates insulin-activated AKT/FOXO3 pathway and promotes granulosa cell apoptosis and dysfunction, therefore affecting oocyte maturation and thus participates in the etiology of ovulation disorder in polycystic ovary syndrome." (PMID 33495419, 2021). "Myo-inositol has an evidence base in reducing BMI in women with polycystic ovarian syndrome (PCOS) and in obese patients with fasting plasma insulin levels but has not been studied in youth." (PMID 32824428, 2020). "However, this antioxidant could not affect hepatic insulin levels in patients with polycystic ovary syndrome (PCOS)." (PMID 33339155, 2020). "We apply the glycerol-insulin model and the OMM to OGTT data from a population of obese and overweight adolescent girls with and without polycystic ovary syndrome (PCOS)." (PMID 35991189, 2022).
polycystic ovary syndrome (continued). "VDBP may also be directly related to insulin regulation, as shown in a study of women with and without polycystic ovary syndrome, where VDBP levels were negatively correlated with serum insulin in both groups independent of the influence of sex hormones including oestrogen and androgen levels." (PMID 32664376, 2020). "Thus, the beneficial mechanism of action of metformin in improving hyperandrogenemia in women with PCOS may be more complicated than at first believed, and independent of its insulin actions." (PMID 25304843, 2014).
Cognitive impairment (571 papers, 2006 to 2026). Abnormal cognition is characterized by deficits in thinking, reasoning, or remembering. "On the one hand, cerebral IR can impair insulin activity and glucose metabolism, exacerbating neuronal cell death, which in turn causes cognitive impairment and dementia." (PMID 41181882, 2026). "Adiponectin reduces inflammatory markers and enhances insulin sensitivity, whereas leptin resistance can induce cognitive impairment by activating inflammatory signals and causing endoplasmic reticulum stress in the hypothalamus." (PMID 41488045, 2025). "Deposition of the Aβ protein, tau protein hyperphosphorylation, and insulin resistance4have been research hotspots in the field of cognitive disorders, and these pathogenic mechanisms coexist in AD, DCI, and VD." (PMID 39814004, 2025). "Type 2 diabetes is a well-known risk factor for cognitive impairment and dementia through impairment of insulin sensitivity, accumulation of Aβ and hyper-phosphorylation of tau protein." (PMID 40397120, 2025). "The RCS analysis revealed a significant non-linear association between eGDR and cognitive impairment incidence, with a higher risk of cognitive impairment observed as eGDR decreased (indicating increased insulin resistance) (P < 0.05)." (PMID 40538401, 2025). "While there is no literature to our knowledge regarding a role of IGFBP5 in FXS, insulin signaling underlies circadian and cognitive deficits in FXS flies and mice." (PMID 40649914, 2025). "Its role in combating cognitive deficits is associated with the regulation of energy metabolism, insulin resistance, Aβ deposition, inflammation, oxidative stress and synaptic plasticity." (PMID 40660735, 2025). "In the future, further prospective research is needed to gain a deeper understanding of the impact of insulin resistance on the risk of cognitive impairment and provide more effective guidance for the prevention and management of cognitive disorders." (PMID 40800025, 2025). "Future research is likely to focus on the associations between nutrition, insulin resistance, synaptic plasticity, and cognitive impairment in AD patients." (PMID 40225337, 2025). "Although the exact mechanisms by which T2DM increases the risk of AD are not fully understood, evidence suggests cognitive impairments in T2DM patients linked to disrupted insulin signaling." (PMID 40905109, 2025). "exercise training is an effective, safe, and practical intervention in the treatment of disorders caused by TD3, including glucose metabolism and insulin signaling, improving inflammation and improving cognitive disorders." (PMID 38238647, 2024). "This study aims to establish the optimal threshold for cognitive impairment risk factors in T2DM patients and compare the efficacy of insulin and metformin in treating mild cognitive impairment (MCI)." (PMID 39220736, 2024). "The impaired ability of neurons to respond to insulin not only disrupts the glucose metabolism but has also been linked with neurodegenerative conditions or cognitive impairments in T2D patients." (PMID 39594636, 2024). "Ferroptosis, implicated in various cognitive impairments, has been effectively alleviated by central insulin treatment." (PMID 39073013, 2024). "As with insulin, hypoglycaemic episodes caused by sulfonylureas can lead to physical injury, cognitive impairment, and increased frailty." (PMID 39338179, 2024). "Recently, there has been particular interest in the procognitive role of insulin as a cognitive modulator and, conversely, the cognitive impairment associated with impaired brain insulin signalling which has major clinical relevance." (PMID 38183680, 2024). "Under pathological conditions, IR is associated with cognitive impairment by affecting the CNS insulin signaling pathway." (PMID 39054513, 2024). "The biological mechanisms underlying this cognitive impairment, explored in animal models, involve inflammation, oxidative stress, insulin resistance, and impaired vascularization." (PMID 38344021, 2024).
Cognitive impairment (continued). "Aging is a primary risk factor for cognitive impairment and exacerbates multiple biological processes in the brain, including but not limited to nutrient sensing, insulin signaling, and histone deacetylation activity." (PMID 38755466, 2024). "We studied the mechanisms of the early period of AD, characterized by nonconvulsive epileptiform activity associated with impaired cerebral insulin signaling and an imbalance in cerebral glucose concentrations, but asymptomatic for cognitive deficits." (PMID 39519239, 2024). "Cognitive impairments are commonly associated with a higher risk of developing dementia and frequently exhibits additional underlying metabolic risk factors, such as insulin resistance and impaired vascular function." (PMID 38703228, 2024). "The cognitive function of patients living with T2DM is intricately linked to insulin signaling, as insulin resistance within the central nervous system emerges as a key mechanism underlying cognitive impairment in these individuals." (PMID 38900771, 2024). "HF diets have been associated with decreased cognitive performance and cognitive impairment by promoting neuronal apoptosis, neuroinflammation, and neuronal insulin resistance, ultimately leading to the pathogenesis of neurological disorders." (PMID 39568732, 2024). "IGFBP5 can modulate lipid metabolism and insulin sensitivity, which are both associated with the cognitive impairment." (PMID 37434738, 2023). "Impaired insulin function in the brain results in sAD-like phenotypes, facilitates loss of synaptic plasticity and causes cognitive deficits." (PMID 38260013, 2023). "Disruption of insulin action in the brain alters neural and glial cell function at the synaptic level and is associated with neurodegenerative and cognitive disorders as well as psychiatric diseases." (PMID 36984824, 2023). "The results of this study showed that hippocampal injection of fibril insulin caused cognitive impairments associated with learning and memory and reduced CA1 as well as DG neurons." (PMID 36856252, 2023). "Since it is known that the process of brain aging can be accompanied by impaired glucose metabolism or reduced glucose supply to the brain, central insulin resistance is associated with an increased risk of cognitive deficit." (PMID 38068904, 2023). "RCT studies have revealed an association between decreased plasma insulin levels and memory improvements in patients with mild cognitive impairments." (PMID 36142570, 2022). "In patients suffering from cognitive disorder and glucose metabolism disorder, metformin enhances insulin susceptibility and lowers fasting insulin levels." (PMID 36077136, 2022). "In this group of patients, risk factors included age, cognitive impairment, previous delirium, use of benzodiazepines and insulin, urinary catheterization, ventricular arrhythmias, hypernatremia, fever, and behavioral strategy." (PMID 35887544, 2022). "It has previously been shown that metabolic dysfunction, including the insulin-signaling pathway, is associated with cognitive impairment, including dementia." (PMID 36418457, 2022). "Recent studies have established that inflammation-associated inhibition of brain insulin signaling plays an important role in neurodegenerative mechanisms leading to synapse damage and cognitive impairments in AD and sepsis." (PMID 36527099, 2022). "TNFα induced the activation of NF-κβ signaling pathway and caspase 3 was associated with diabetic-induced cognitive deficits and insulin combination with tocotrienol exhibited promising cognitive enhancement in the diabetic rats." (PMID 34108878, 2021). "In aged rats as well, surgical procedures impair central insulin signaling and increase susceptibility to hippocampus-related cognitive impairments." (PMID 34512303, 2021).